ABCG2 (ATP binding cassette subfamily G member 2 (JR blood group))
Diseases named in the same sentence as ABCG2 in open-access papers (continued):
Sharing a sentence is not in itself a finding about the gene and the disease.
cancer (continued). "An effective way to reverse MDR and increase the sensitivity of cancer cells to chemotherapy drugs is to inhibit the expression of ABCG2, thereby blocking the drug efflux mediated by it." (PMID 38735927, 2024). "In both LUAD and LUSC samples, the hypomethylated ABCG2 promoter region was significantly less methylated in cancer samples than normal samples (p < 0.001)." (PMID 39457707, 2024). "Targeting ABCG2-mediated drug efflux therefore has emerged as a promising strategy for combating chemoresistance and improving treatment results in cancer patients." (PMID 39850800, 2024). "Three major transporters—P-glycoprotein (P-gp or ABCB1), multidrug resistance protein 1 (MRP1 or ABCC1), and breast cancer resistance protein (BCRP or ABCG2) are notoriously involved in therapy resistance in cancer patients." (PMID 38766631, 2024). "ABCG2 is extensively expressed in some cancer stem cells and its expression is often increased in response to chemotherapy, which helps these cells surviving treatments." (PMID 39850800, 2024). "Our studies propose that RN486 can antagonize ABCG2-mediated MDR in cancer cells via down-regulating the expression level of ABCG2 protein, reducing ATPase activity of ABCG2 transporter, and inhibiting the transporting function." (PMID 39081282, 2024). "As c-MYC, also one other HLH transcription factor, E2F1 is often overexpressed in many cancers and acts by directly bonding the ABCG2 promoter, activating protein transcription, and inducing chemotherapy resistance." (PMID 38255216, 2024). "In pancreatic cancer cell lines, knockout Nrf2 re-sensitized cancer cells to 5-Fluorouracil by suppressing ABCG2 expression." (PMID 38255216, 2024). "ABCG2 is a multidrug transporter that protects tissuesfrom xenobiotics,affects drug pharmacokinetics, and contributes to multidrug resistanceof cancer cells." (PMID 39445888, 2024). "The ability of ABCG2 to expel a wide range of drugs from cancer cells enables these cells to evade the cytotoxic effects of chemotherapy." (PMID 39403600, 2024). "Nevertheless, the prolonged effect of MTX-211 treatment on ABCG2 expression in cancer patients remains to be elucidated." (PMID 38791198, 2024). "Eph receptor B2 (EphB2), an important member of the ephrin receptor family, can stimulate ABCG2 expression in other types of cancer cells, which can explain the correlation observed in our study." (PMID 39457707, 2024). "The overexpression of ExomiR-328 is seen to negatively regulate the expression of breast cancer resistance protein (BCRP/ABCG2) in human cancer cells leading to mitoxantrone resistance." (PMID 38455764, 2024). "Conditioned medium from chemotherapy-treated MAFs raised the expression of cancer stem cell markers, including ABCG2 and CD44, in the recipient mPDOs." (PMID 38791392, 2024). "The inactivation of ferrochelatase and ABCG2 in cancer cells leads, on the one hand, to impaired heme production and the impaired excretion of protoporphirin IX." (PMID 38256035, 2024). "This specific localization pattern correlates with the CSC theory of cancer, supporting the role of ABCG2 in maintaining the stem cell phenotype and its contribution to the resilience of these tumors to chemotherapy." (PMID 38542090, 2024). "Non-toxic concentrations of RN486 remarkably increased the sensitivity of ABCG2-overexpressing cancer cells to conventional anticancer drugs mitoxantrone and topotecan." (PMID 39081282, 2024). "Breast cancer resistance protein (BCRP or ABCG2) is involved in cancer multidrug resistance and transports anticancer drugs out of cells." (PMID 38691224, 2024). "As a result, the cytotoxicity and effectiveness of MTX-211 in suppressing the activation of the EGFR and PI3K pathways were significantly attenuated in cancer cells overexpressing ABCG2." (PMID 38791198, 2024). "So far, the knowledge about the mechanisms of the transcriptional regulation of ABCG2 expression remains limited in most types of human cancers." (PMID 39457707, 2024).
cancer (continued). "We showed that the drug efflux activity of ABCG2 substantially decreased the intracellular accumulation of MTX-211 in cancer cells." (PMID 38791198, 2024). "Subsequently, we verified these findings by assessing the MTX-211 cytotoxicity in HEK293 cells and HEK293 cells transfected with human ABCG2 (R482-HEK293), demonstrating that ABCG2 confers resistance to MTX-211 in cancer cells and the ABCG2-transfected cells." (PMID 38791198, 2024). "Although an FDA-approved ABCG2 inhibitor is currently unavailable, our study demonstrates the potential principle that inhibiting ABCG2 function can restore the efficacy of MTX-211 in ABCG2-overexpressing multidrug-resistant cancer cells." (PMID 38791198, 2024). "ABCG2 actively remove a variety of chemotherapeutic drugs out of cancer cells, lowering intracellular drug accumulation and effectiveness." (PMID 39850800, 2024). "Apart from ABC transporters upregulated in numerous cancers (P-glycoprotein, multidrug resistant protein-1), breast cancer resistance proteins (BCRP/ABCG2), initially cloned from a multidrug-resistant BC cell line, play a crucial role." (PMID 39269086, 2024). "Some studies have suggested that upregulation of ABC family proteins such as ABCB1, ABCC1 and ABCG2, which transport chemotherapeutic drugs out of cancer cells, is the main reason for chemoresistance in cancer cells." (PMID 38228910, 2024). "The reversal mechanistic studies showed that RN486 elevated the drug accumulation because of reducing the eflux of ABCG2 substrate drug in ABCG2-overexpressing cancer cells." (PMID 39081282, 2024). "At least 11 ABC transporters have been implicated in multi-drug resistance, including P-glycoproteins (P-gp/ABCB1), multi-drug resistance proteins (MRP/ABCC), and breast cancer resistance proteins (BCRP/ABCG2)." (PMID 40034145, 2024). "Moreover, ABCG2 has been implicated in conferring resistance to various chemotherapy drugs, including topotecan, SN-38, mitoxantrone, doxorubicin, and several tyrosine kinase inhibitors (TKIs), contributing to multidrug resistance in cancer, as observed in colon cancer." (PMID 38397468, 2024). "The presence of ABCG2 in both cancer cells and the endothelium of blood vessels suggests a multifaceted role in physiological processes, such as the protection against xenobiotics, and in the pharmacokinetics of drugs." (PMID 38542090, 2024). "The mechanism of action of furmonertinib was characterized through ATPase assays, revealing its interaction with ABCB1 and ABCG2,suggesting a potential strategy to overcome resistance in EGFR exon 20ins-mutated cancers." (PMID 39743996, 2024). "Flavonoids as ABCG2 inhibitors can sensitize cancer stem cells to the activity of standard chemotherapy including estrogenic compounds." (PMID 39519572, 2024). "Given the role of ABCG2 in the efflux of a broad range of chemotherapeutics, translating ABCG2 inhibitors into the clinic is an attractive strategy in cancer." (PMID 39033209, 2024). "Significantly, the ABCG2 inhibitor Ko143 (1 μM) notably increased the MTX-211-induced apoptotic cell count from 7% basal to 55% in S1-MI-80 cancer cells." (PMID 38791198, 2024). "The connection between ABCG2-expressing cancer cells and blood vessels is significant for several reasons." (PMID 38542090, 2024). "Organoid formation and expression of cancer stem cell markers such as ABCG2, NANOG, and CD44 were altered by conditioned media from treated MAFs." (PMID 38791392, 2024). "Doxorubicin is a well-known substrate of both ABCB1 and ABCG2 and an effective chemotherapy drug that has been shown to hinder cancer proliferation of multiple solid tumors." (PMID 38589905, 2024). "The isolated cancer-stem like side population cells from NPC demonstrated increased expression of ABCG2 and the anti-apoptotic factor Bmi-1." (PMID 38254110, 2024).
cancer (continued). "Irinotecan faces limitations owing to its decreased intracellular concentration in cancers with ABCG2 overexpression, where it acts as a substrate for the ABCG2/BCRP efflux pump, a mechanism contributing to drug resistance." (PMID 39410005, 2024). "FL118, another camptothecin (CPT) analog, avoids expulsion from cancer cells via the ABCG2/BCRP pump and maintains its intracellular efficacy." (PMID 39410005, 2024). "In the present study we show that, in addition to its chemoprotective role in cancer cells, ABCG2 can regulate cancer cell metabolism via regulation of the glutamine transporter SLC1A5, resulting in increased glutaminolysis and enhanced redox regulation." (PMID 38641063, 2024). "Herein, we shifted the experimental setting to human cancer cell lines and combined treatment of ABCG2 inhibitors and cytostatic drugs, displaying three synergistic combinations in MCF-7 Doxo, three in SW480, and two in HT29 cell lines." (PMID 38004447, 2023). "After heterodimerizing with RXR, the PPARγ/RXR complex binds to the PPAR response element upstream of the Abcg2 promotor, which induces drug resistance in cancer cells (Nakanishi and Ross, 2012)." (PMID 36973040, 2023). "CBD targets have been suggested to play a role in cancer therapy resistance, including breast cancer resistance protein (ABCG2/BRCP), bile salt export pump (ABCB11/BSEP), and p-glycoprotein (p-gp)." (PMID 36769206, 2023). "In the context of GBM, transcriptional activation of NANOGP8 confers stemness to cancer cells and affects the downstream genes, e.g. ABCG2, a multigene drug transporter gene responsible for drug efflux." (PMID 36696426, 2023). "Imperatorin at 10 μM notably inhibited the function of ABCG2 and restored the intracellular accumulation of PhA in ABCG2-overexpressing S1-MI-80 and H460-MX20 cancer cells, and ABCG2-transfected R482-HEK293 cells." (PMID 38004460, 2023). "The cytotoxicity of HS-173 in several pairs of ABCB1- and ABCG2-overexpressing cancer cell lines and the respective parental cell lines was established to elucidate the impact of ABCB1 and ABCG2 on the efficacy of HS-173 in cancer cells." (PMID 37048130, 2023). "Methyl-cantharidimide plays a critical role in reducing cisplatin resistance at ABCB1- and ABCG2-overexpressing cancer cells." (PMID 37202806, 2023). "ABCB1/P‐gp (P‐glycoprotein), multidrug resistance‐associated protein 1 (ABCC1/MRP1) and breast cancer resistance protein (ABCG2/BCRP) are the most studied ABC transporters with well‐established roles in mediating multidrug resistance in cancer cell models." (PMID 38102848, 2023). "ABCG2 protein expression analysed by IHC showed that ABCG2-positive cells were mainly positioned in the cancer’s invasion front, and strong membranous staining was significantly correlated with a higher Dukes’ stage and distant metastases." (PMID 38067326, 2023). "In vitro studies on cancer cell lines seem to confirm their ability to downregulate ABCG2 at transcription or post-translational level." (PMID 37108308, 2023). "To unravel the potential mechanism by which imperatorin sensitizes cancer cells overexpressing ABCG2, we conducted investigations into its impact on both the drug transport function and protein expression of ABCG2 in these cells." (PMID 38004460, 2023). "Our results indicate that HS-173 efflux mediated by ABCB1 and ABCG2 significantly contributed to the reduced efficacy of HS-173 in these cancer cells." (PMID 37048130, 2023). "In fact, several ABC transporters are used as markers for TICs in certain cancer types (i.e., ABCG2 is a TIC marker in lung, liver, and prostate cancer)." (PMID 37108784, 2023). "In summary, our data show the interactions of HS-173 with ABCB1 and ABCG2, as well as providing experimental evidence that the overexpression of ABCB1 or ABCG2 in cancer cells is a novel mechanism of acquired resistance to the PI3K inhibitor HS-173." (PMID 37048130, 2023).
cancer (continued). "Taken together, our results demonstrate that the efficacy of HS-173 was reduced by the drug-transport function of ABCB1 and ABCG2 in cancer cells." (PMID 37048130, 2023). "Therapeutic treatment with ABCG2 inhibitors primarily aims to increase the sensitivity of cancer cells to cytostatic drugs or to reverse transporter-mediated drug resistance." (PMID 38004447, 2023). "Prior to the elucidation of the compounds’ influence on the cell viability, we have determined the levels of ABCB1 and ABCG2 expression in different cancer cell lines." (PMID 38004447, 2023). "ABCG2 can protect cells against compounds initiating and/or intensifying neoplasia and is considered a marker of stem cells responsible for cancer growth, drug resistance and recurrence." (PMID 37445716, 2023). "It is noteworthy that due to the presence of a trace amount of ABCG2 protein in the parental H460 cell line, we observed a noticeable chemosensitization effect by furmonertinib in H460 cancer cells." (PMID 37762275, 2023). "The knockdown of PFKFB3 inhibits the expression of cancer stemness markers such as CD133, ALDH1A1, CD44, Sox2, and ABCG2, which are also associated with chemotherapy resistance." (PMID 37919747, 2023). "To this end, we examined the effect of HS-173 on MDR mediated by ABCB1 and ABCG2 in cancer cells overexpressing ABCB1 or ABCG2." (PMID 37048130, 2023). "We found that the overexpression of ABCB1 or ABCG2 significantly reduced the efficacy of HS-173 in human cancer cells." (PMID 37048130, 2023). "Increased expression of the resistance genes ABCG2 and ERBB2, the CSC gene ALDH1A3, as well as the EMT gene SNAI1 after 5-FU treatment in PDSs were linked to ER-negative status of the primary cancer." (PMID 38124067, 2023). "Cancer cells with high glycolysis can release a large number of exosomes containing cancer stemness markers, including ABCG2, ALDH1A1, and EpCAM." (PMID 37919747, 2023). "Recently, substantial endeavors have been dedicated to identifying bioactive compounds isolated from nature capable of counteracting ABCG2-mediated MDR in cancer cells." (PMID 38004460, 2023). "ABCG2 can export anticancer drugs from cancer cells, and its high expression in human group 3 medulloblastoma cells was shown to cause chemoresistance." (PMID 37438132, 2023). "In contrast, tariquidar and Ko143 completely reversed MDR mediated by ABCB1 and ABCG2 in these cancer cell lines." (PMID 37048130, 2023). "Both the ABCG2 gene and protein expression have aroused considerable interest as potential prognostic factors in various cancers." (PMID 37445716, 2023). "Our research revealed that imperatorin, when administered at sub-toxic concentrations, exhibits a distinct ability to selectively re-sensitize multidrug-resistant cancer cells that overexpress ABCG2 to antiproliferative drugs." (PMID 38004460, 2023). "The ABC superfamily includes various important proteins associated with cancer resistance to cytostatics, such as multidrug resistance protein 1 (MRP1 and ABCC1), breast cancer resistance protein (BCRP and ABCG2), glycoprotein P (Pgp and ABCB1), and ABCB5." (PMID 38136555, 2023). "It has been shown that the ABCG2 ATPase activity is required for the active transport of substrates from cancer cells." (PMID 37521473, 2023). "ABCG2-inhibiting compound QCe exhibited further synergistic effects with doxorubicin and cisplatin in ABCG2-expressing cancer cells." (PMID 38004447, 2023). "Decreased ABCG2 mRNA expression (blue) was observed in all except one analysed cancer, i.e., including various breast, ovarian, lung and liver tumours." (PMID 37445716, 2023). "In general, the overactivation of ABCG2 functions as a critical contributor to drive cancer cell chemoresistance and metastasis." (PMID 37708089, 2023). "Recently, drug repurposing has emerged as a feasible strategy to overcome ABCB1- or ABCG2-mediated drug resistance in cancer." (PMID 37521473, 2023).
cancer (continued). "Hitherto, the knowledge about the expression regulation of ABCG2, in particular its upstream transcriptional regulatory mechanisms, remains limited in cancer, including CRC." (PMID 37708089, 2023). "Being aware that numerous EGFR inhibitors had been previously discovered as modifiers of ABCB1 and/or ABCG2, we explored the potential of furmonertinib to enhance chemosensitivity in multidrug-resistant cancer cells that overexpress ABCB1 or ABCG2." (PMID 37762275, 2023). "ABCG2 was initially cloned from a drug-resistant cancer cell but ultimately was found to have a different substrate profile than the ABCG2 protein cloned from the normal tissue." (PMID 37438132, 2023). "In the present work, we identified two out of three tested cancer associated ABC transporters, ABCB1/MDR1 and ABCG2/BCRP, as off-targets of the OGG1 inhibitors TH5487 and SU0268." (PMID 36819096, 2023). "This study investigates the chemosensitizing potential of imperatorin in ABCG2-overexpressing cancer cells." (PMID 38004460, 2023). "Several studies have reported that some PI3K inhibitors are able to reverse MDR mediated by ABCB1 and/or ABCG2 in cancer cell lines." (PMID 37048130, 2023). "In this in vitro study, we conducted in vitro experiments to determine if MK-2206 attenuates multidrug resistance in cancer cells overexpressing the ABCB1 or ABCG2 transporter." (PMID 37521473, 2023). "TOX3 overexpression reversed the inhibition at the transcription of ABCG2, the expression of cancer stem-like traits-related genes, clonogenicity, spheroid formation, and CSC frequency induced by WDR5 knockdown, and vice versa." (PMID 37708089, 2023). "In order to substantiate cytotoxicity and growth retardation caused by a drug substrate of ABCG2, the effect of imperatorin on apoptosis induced by topotecan was explored in S1-MI-80 and H460-MX20 cancer cells." (PMID 38004460, 2023). "The high expression of the ATP-binding cassette (ABC) drug transporter ABCG2 in cancer cells contributes to the emergence of multidrug resistance (MDR) in individuals afflicted with either solid tumors or blood cancers." (PMID 38004460, 2023). "In the process of mediating drug resistance of tumor cells, ABCG2 recognizes and effectively squeezes out various chemotherapeutic drugs with different chemical structures, resulting in drug resistance of cancer cells." (PMID 37919637, 2023). "In the current study, cCSCs were enriched by spheroid formation upon chemotherapeutic treatment, and ABCG2 was focused among the up-regulated genes in cCSCs by comparation to the adherent cancer cells." (PMID 37708089, 2023). "In the present investigation, we detailed the modulatory effects of imperatorin on ABCG2-mediated MDR in multidrug-resistant cancer cells." (PMID 38004460, 2023). "In this study, we investigate the potential of repurposing furmonertinib, an epidermal growth factor receptor (EGFR) tyrosine kinase inhibitor (TKI), as a candidate for reversing MDR mediated by ABCB1 and ABCG2 in multidrug-resistant cancer cells." (PMID 37762275, 2023). "This short review mainly focuses on those three ABC transporter members (ABCB1, ABCC1 and ABCG2), which are predominantly linked to the phenomenon of MDR in cancer therapy." (PMID 36677553, 2023). "Given the results above, we assumed that WDR5 tri-methylates H3K4 at ABCG2 promoter to further recruit TOX3 resulting in the up-regulation of ABCG2 transcription and ultimately in the development of cancer stem-like traits and drug resistance." (PMID 37708089, 2023). "More importantly, oftentimes ABCB1 and/or ABCG2 overexpression gives rise to the development of multidrug resistance (MDR) in cancer cells." (PMID 37048130, 2023). "Nevertheless, when considering MDR, ABCG2 (ATP-binding cassette superfamily G member 2) is the most remarkable member for its high expression in cancer cells and in cancer stem cells." (PMID 37092502, 2023).